CETP (cholesteryl ester transfer protein)
Diseases named in the same sentence as CETP in open-access papers (continued):
Sharing a sentence is not in itself a finding about the gene and the disease.
Obesity (63 papers, 2009 to 2025). Accumulation of substantial excess body fat. "Overall, we report six genetic variants of ADIPOQ, FTO and LEPR genes as obesity-risk markers and a CETP gene variant as lean mass/obesity protective marker in studied Pakistani cohort." (PMID 36126070, 2022). "The only genetic variant which not only showed protective association towards obesity but significant positive association with lean body mass was rs3764261 SNP of CETP gene." (PMID 36126070, 2022). "In the present study, we found that obesity was associated with marked changes in CETP and LCAT activities and altered HDL composition, such as decreased apoA-I, cholesterol, and phospholipid levels, while serum amyloid a levels were increased." (PMID 33673728, 2021). "CETP Taq1B polymorphism was found to be able to increase the association between dietary insulin indices and obesity." (PMID 34354158, 2021). "Some findings revealed that the CETP polymorphism interacts with dietary carbohydrate intake on metabolic factors, such as hypertension, dyslipidemia, obesity, insulin resistance (IR) and DM19." (PMID 34354158, 2021). "The CETP-expressing mice were relatively protected against the decline in exercise capacity caused by obesity." (PMID 26313355, 2015). "Differential methylation is found within genes associated with obesity, epigenetic regulation and development, such as CETP, FOXP2, HDAC4, DNMT3B, KCNQ1 and HOX clusters." (PMID 25651499, 2015). "Since glycolysis provides an important energy source for working muscle, we aimed to define if CETP expression protects against the decline in exercise capacity associated with obesity." (PMID 26313355, 2015). "Female CETP transgenic mice were relatively protected against the decline in exercise capacity caused by obesity compared to WT." (PMID 26313355, 2015). "The CETP concentration and activity in plasma is dependent on several factors such as environmental components including dietary cholesterol, alcohol, smoking and obesity, gender, and genetic influence (e.g. polymorphism of CETP gene)." (PMID 19558660, 2009). "In addition, some findings have revealed the interactions between CETP polymorphism and dietary carbohydrate intake in relation to metabolic factors such as obesity and diabetes mellitus." (PMID 38062157, 2023). "Differential methylation was found in genes associated with obesity, epigenetic regulation and development, such as cholesteryl ester transfer protein (CETP), forkhead box P2 (FOXP2), HDAC4, DNMT3B, potassium voltage-gated channel subfamily Q member 1 (KCNQ1) and homeobox (HOX) clusters." (PMID 36397166, 2022). "The ‘A’ allele of the SNP rs4783961 has been shown to influence the concentration of CETP mass in plasma by producing binding motifs for transcription factor SP3, which modulates CETP promoter activity, but studies examining the association of rs4783961 with obesity traits are limited." (PMID 35807893, 2022). "Nonetheless, association of other CETP SNPs with obesity traits have been previously reported." (PMID 35807893, 2022). "Additionally, CETP polymorphisms was associated with an elevated risk of obesity and obesity-related diseases." (PMID 34354158, 2021). "Lower CETP plasma levels are correlated with a lower obesity risk." (PMID 21767357, 2011). "Therefore, the obesity-associated increase in CETP production is thought to affect HDL-C levels." (PMID 33256096, 2020). "In this research, we studied the anti-obesity effects of butyrate in the high-fat diet-induced obese humanized APOE*3-Leiden.CETP mouse model." (PMID 40002674, 2025). "This research aimed to determine the interaction of the rs708272 polymorphism of CETP and the fatty acid intake with changes in the HOMA-IR in adults living with overweight or obesity." (PMID 39519516, 2024).
Obesity (continued). "Previously, it has been reported that the genetic variants in ADIPOQ, CETP, FTO, LEP, and LEPR genes are strongly correlated with obesity and associated metabolic complications in different ethnicities of the world." (PMID 36126070, 2022). "Studies examining CETP and obesity have mainly focused on the impact of body weight on CETP mass and activity." (PMID 35807893, 2022). "Another important candidate gene for the study is CETP, the SNPs in which have been reported to influence obesity and lipid-related traits." (PMID 35807893, 2022). "We used transgenic mice with a human CETP minigene (huCETP) controlled by its natural flanking region to further understand CETP-related physiology in response to obesity." (PMID 35082691, 2021). "E3L.CETP mice fed the HFC diet developed pronounced obesity (as compared to age-matched control mice fed a low fat chow diet) within 15 weeks that remained stable until 25 weeks." (PMID 33658534, 2021). "It is well known that male mice are more susceptible to diet-induced obesity than female mice, and this also holds true for APOE*3-Leiden.CETP mice (unpublished observations)." (PMID 32915671, 2020). "In the state of obesity, increased CETP levels are correlated with leptin levels, in line with the fact that adipose tissue is one of the major sources of CETP expression." (PMID 33256096, 2020). "We analysed the potential interactions between respective CETP genotypes and traditional CAD risk factors (male gender, cigarette smoking, hypertension, overweight/obesity, and plasma lipid abnormalities)." (PMID 30178218, 2018). "Upon a high fat diet (HFD) but not upon a low fat diet (LFD), mice expressing the mutant apoE3Leiden and CETP (E3L*CETP) develop obesity, fatty liver, and insulin resistance." (PMID 30250222, 2018). "The results herein demonstrate that CETP expression protects female mice from the obesity-related decline in exercise capacity." (PMID 26313355, 2015). "In summary, we proposed that 4-week rimonabant treatment has a moderate effect on liver lipid metabolism in the early stage of obesity of ApoE*3Leiden.CETP mice under current experimental conditions." (PMID 21611179, 2011). "The effects of rimonabant on lipid metabolism and body weight reduction in the early stage obesity were shown to be moderate in ApoE*3Leiden.CETP mice on high-fat diet." (PMID 21611179, 2011). "Our 4-week rimonabant treatment of ApoE*3Leiden.CETP transgenic mice in early stage of obesity showed similar reduction of plasma TC and a reduction trend of plasma TG." (PMID 21611179, 2011). "The findings also demonstrate the potential beneficial effects of calcium channel blockers on cSVD imaging markers and cholesteryl ester transfer protein inhibitors, lipoprotein lipase enhancement and gastric inhibitory polypeptide receptor obesity-targeted drugs on LS." (PMID 39661645, 2025). "Another study provided the first evidence that butyrate (oral but not intravenous administration) improved energy metabolism via the gut–brain neural circuit in a cholesteryl ester transfer protein (CETP) mouse model (a translational model for diet-induced obesity akin to that in humans)." (PMID 37047387, 2023). "The mechanism under which rs4783961 affects obesity traits are unclear, although it has been proposed that CETP SNPs might affect deposition of fat in visceral adipose tissue by being in linkage with SNPs of other genes." (PMID 35807893, 2022). "With the persistent status of high triglyceride-enriched VLDL particle concentration in people with obesity, cholesteryl ester transfer protein (CETP) promotes the exchange of cholesteryl esters from LDL particles and HDL particles for triglycerides from VLDL particles." (PMID 36387872, 2022). "CETP and LPL SNPs have also been associated with obesity-related traits." (PMID 35807893, 2022).
Obesity (continued). "In summary, we reproduced NASH development with progression to fibrosis in HFC-fed E3L.CETP mice, a model that is characterized by obesity, metabolic anomalies and histopathological features and underlying disease pathways similar to those observed in human NASH." (PMID 33658534, 2021). "Although several studies have reported an association between DIL and DII scores and obesity, the interaction between DII and DIL with CETP polymorphism on obesity was not evaluated yet." (PMID 34354158, 2021). "The key findings of the current study were the significant interaction result of CETP rs708272 polymorphism with DIL and DII on obesity indices (WC and BMI), lipid profiles (TG, HDL, LDL/HDL), inflammatory markers (IL-18, CRP, and PGF2α), and antioxidant markers (TAC and SOD) in T2DM patients." (PMID 34354158, 2021). "ApoE*3Leiden.CETP mice rapidly developed obesity and were highly prone to cartilage degradation." (PMID 32456298, 2020). "Elevation in the CETP might be a key player in HDL metabolism during obesity progression, accumulating in visceral fat to impair the lipoprotein levels, antioxidant activity, and lipoprotein functionality." (PMID 30072955, 2018). "Our previous studies have suggested that transgenic expression of cholesteryl ester transfer protein (CETP) in mice may protect against obesity-related declines in exercise capacity." (PMID 26313355, 2015). "CETP activity and liver CETP gene expression are induced in with obesity in men and women." (PMID 26313355, 2015). "We selected five of these (ACACA, CETP, CTGF, S100A8, S100A9) for further analyses based on reported adipose or adipocyte gene expression changes in response to weight loss/dietary intervention (ACACA, CETP, CTGF), and/or associations with obesity or related traits (GWAS, and/or other literature)." (PMID 25651499, 2015). "Based on our study, we proposed that the rimonabant intervention on early obesity of ApoE*3Leiden.CETP mice would affect plasma and hepatic lipid metabolism relative to the non-treated controls, leading to increased HDL-C concentrations and decreased VLDL/LDL-C levels." (PMID 21611179, 2011). "The involvement of CETP in intramuscular fat deposition was shown in another animal study, and it was also demonstrated that in transgenic female mice, CETP can protect against obesity-induced impairment in exercise capacity and may be a target to improve exercise capacity in the context of obesity." (PMID 39201274, 2024). "In obesity, levels of HDL-C are low due to increased leptin, increased CETP production, decreased adiponectin, increased HDL-C clearance by hepatic and endothelial lipase, and reduced cholesterol efflux to HDL-C in adipocytes." (PMID 38004588, 2023). "Cholesteryl ester transfer protein (CETP), which is synthesized by the liver, can also reduce obesity by enhancing lipolysis and brown adipose tissue activity." (PMID 37383400, 2023). "Of note, the increase in HDL-C levels in CETP-TaqIB, B2B2 carriers seemed to be independent from sexual hormones and was lost in obesity and type 2 diabetes (T2D)." (PMID 36304545, 2022). "In the current study we investigated the response of elafibranor in APOE*3Leiden.CETP mice, a translational animal model that displays histopathological characteristics of NASH in the context of obesity, insulin resistance and hyperlipidemia." (PMID 33658534, 2021). "There was a positive correlation between CETP activity and fasting LDL-C levels in children with type 1 diabetes and obesity." (PMID 34222380, 2021). "Cholesteryl ester transfer protein (CETP), a protein involved in replacing lipids between lipoproteins, improves insulin sensitivity in obesity through increased cholesterol delivery to liver and activation of bile acid-sensitive pathways." (PMID 32586392, 2020). "The activity of hepatic lipase is increased in obesity and insulin resistance, leading to faster clearance of triglyceride-rich HDL, which is produced by CETP-mediated transfer." (PMID 33256096, 2020).
Obesity (continued). "In this trial and in 1,611 participants of the Netherlands Epidemiology of Obesity (NEO) study, we measured HTGC and circulating CETP by proton magnetic resonance spectroscopy and ELISA, respectively." (PMID 31292457, 2019). "Thus because CETP has a large natural variability, and declines with progression to diabetes, understanding how this pathway may be augmented to improve exercise capacity with obesity may be a new therapeutic opportunity." (PMID 26313355, 2015). "Co-localization analysis suggested that LPL (as a TG-lowering drug target), CETP (as an HDL-raising drug target), ABCC8 (as a glucose-lowering drug target) and GIPR (as an anti-obesity drug target) were unlikely to share a causal variant with LS." (PMID 39661645, 2025). "Additionally, we observed the potential beneficial effects of CCB-targeted drugs on cSVD imaging markers and of CETP-targeted, LPL-targeted and GIPR obesity-targeted drugs on LS." (PMID 39661645, 2025). "Thus, our results demonstrate that CETP and APOA2 SNPs can be suggested as key elements for genotype-based precision medicine for obesity." (PMID 38062157, 2023). "However, an anti-adipogenic effect of CETP in the presence of apolipoprotein CIII (apoCIII) was reported by an animal study involving CETP and apoCIII transgenic mice, where obesity induced by a high-fat diet was reversed by the expression of CETP." (PMID 35807893, 2022). "While high-fat diet feeding induced obesity for huCETP mice and their wild-type littermates lacking CETP expression, insulin sensitivity was higher for female huCETP mice than for their wild-type littermates." (PMID 35082691, 2021). "Obesity and hyperlipidemia are known to significantly impact aspects of cholesterol metabolism and HDL biology and may impact aspects of CETP-mediated biology." (PMID 35082691, 2021). "What’s more, some key enzymes involved in HDL metabolism, such as cholesteryl ester transfer protein (CETP), lecithin/cholesterol acyltransferase (LCAT), hepatic lipase (HL) and protein phospholipid transfer protein(PLTP), are changed in people with obesity who have insulin resistance." (PMID 31842884, 2019). "Because obesity induces a decline in exercise capacity, we measured the changes in exercise capacity in CETP-expressing female mice and their non-transgenic littermates over a period of HFD-feeding." (PMID 26313355, 2015). "Furthermore, female APOE∗3-Leiden.CETP mice are not prone to develop obesity and related pathologies, such as insulin resistance and intramuscular lipid accumulation." (PMID 37356205, 2023). "The selected features of the proposed classifier on the Set 1 were CETP TaqIB [rs708272], CETP A373P [rs5880], LPL D9N [rs1801177], ApoE, ABCAI R1587K [rs2230808], APOA5 C-1131T [rs662799], LPL HindIII [rs320], APOC3 SstI [rs5128], family history of obesity, and diabetes, and APOA1 MspI [rs2893157]." (PMID 30026888, 2018). "Moreover, obesity-induced insulin resistance and diabetes stimulate synthesis of the triglyceride-rich lipoprotein VLDL, which can lower HDL cholesterol by augmenting the transfer from HDL to VLDL via the cholesteryl ester transfer protein." (PMID 27378920, 2016).
diabetes (53 papers, 2005 to 2025). "Cholesteryl ester transfer protein (CETP) inhibitors, initially developed for treating hyperlipidemia, have shown promise in reducing the risk of new-onset diabetes during clinical trials." (PMID 38962682, 2024). "As pointed out, higher HDL-C levels are associated with lower risk of diabetes, and so is CETP inhibition." (PMID 34849601, 2022). "Accordingly, a pharmacological increase of HDL with CETP inhibitors was associated with a significant rise in insulin plasma concentration and with a significant risk reduction of new onset of diabetes in patients treated with dalcetrapib." (PMID 35625916, 2022). "Cholesteryl ester transfer protein inhibitors (CETPis) are a class of lipid lowering medications with potential to lower the risk of new onset diabetes." (PMID 35441656, 2022). "Through drug target MR we show that on-target CETP inhibition is predicted to reduce the risk of several cardiovascular endpoints and diabetes but potentially increase the risk of age-related macular disease (AMD)." (PMID 34561430, 2021). "Increased plasma CETP activity consequent to diabetes-associated hypertriglyceridemia results in lower HDL cholesterol and smaller HDL particles." (PMID 32245262, 2020). "We assess the selection performance of POINT using simulations and illustrate how it can be used to prioritize individual rare variants in PCSK9, ANGPTL4 and CETP in the Action to Control Cardiovascular Risk in Diabetes (ACCORD) clinical trial data." (PMID 30779729, 2019). "We herein examined the influence of the CETP status on the lipid-reducing effects of pitavastatin in hypercholesterolemic patients with type 2 diabetes mellitus as well as the molecular mechanism underlying pitavastatin-induced modifications in CETP levels." (PMID 26984517, 2016). "In assessment of association between CAD and diabetes in Iranian population the following genes showed significant association: paraoxonase 1, adiponectin, eNOS, CETP, AT1R, resistin, MMP-3, BChE K, Apo E, ACE." (PMID 26587547, 2015). "However, we observed statistically significant differences in glycated hemoglobin, diabetes risk, and lipid parameters related to CETP and SGLT2." (PMID 38962682, 2024). "Thus, we explored the interaction between CETP TaqB1 polymorphism with dietary acid load (DAL) on lipid profile among type 2 diabetes mellitus (T2DM)." (PMID 37407953, 2023). "Finally, a recent meta-analysis demonstrated that CETP inhibitors decrease the risk of new-onset of diabetes by 16%, concomitantly with significant increases in HDL-C." (PMID 35625916, 2022). "The precise mechanism underlying the reduced HDL-C level in diabetes mellitus is unknown but may be a consequence of increased activities of cholesteryl ester transfer protein and endothelial lipase." (PMID 34944763, 2021). "CETP is a key regulator of lipid metabolism and polymorphism of the gene may be associated with complications of diabetes mellitus." (PMID 15992403, 2005). "Notably, a CDKAL1 variant (rs7766070) confers the highest level of risk while rs7119 (HMG20A) and rs708272 (CETP) have high risk allele frequencies in this population at 0.77 and 0.66, respectively, making them potentially good markers for type 2 diabetes mellitus screening." (PMID 39561140, 2024). "CETP activity is also found to be increased in states of high oxidative stress, such as in type 2 diabetes mellitus, and may partially explain the predisposition of diabetics to cardiovascular disease 81,82." (PMID 35836811, 2022). "Thus, the increase in HDL following CETP inhibition may very well explain the reduction of diabetes risk as observed in the CVOT trials." (PMID 34849601, 2022). "However, whether CETP genetic variations impact on the risk of developing diabetes is controversial." (PMID 31597401, 2019). "In diabetes, insulin resistance, hyperglycemia, and hyperinsulinemia lead to activation of cholesteryl ester transfer protein, which is responsible for increased HDL-c catabolism." (PMID 39669850, 2024).